CELA2B (chymotrypsin like elastase 2B)
Description:
Acts upon elastin.
Synonyms: ELA2B; RP11-265F14.2
Tractability: Antibody: its Gene Ontology location is reachable by antibodies, with high confidence; UniProt places it where antibodies can reach, with medium confidence; UniProt predicts a signal peptide or a membrane-spanning region.
Gene: Protein-coding gene on chromosome 1 (15,465,909 to 15,491,395, forward strand). Ensembl gene ENSG00000215704.
Subcellular location: Secreted
Gene Ontology:
Molecular function: protein binding; serine-type endopeptidase activity
Biological process: insulin catabolic process; proteolysis; regulation of platelet aggregation
Cellular component: extracellular region
Genetic constraint (gnomAD): Loss-of-function variants: 26 observed, 36.55 expected, observed/expected ratio (o/e) 0.71, 90% interval 0.52 to 0.99. The upper end of that interval is the gene's LOEUF score, 0.99, which puts it in group 4 of 6, group 1 being the genes least tolerant of losing a copy. Missense variants: 324 observed, 347.1 expected, observed/expected ratio (o/e) 0.93, 90% interval 0.85 to 1.02. Synonymous variants: 136 observed, 146.56 expected, observed/expected ratio (o/e) 0.93, 90% interval 0.81 to 1.07.
Homologues: Orthologues: chimpanzee CELA2B (97% identical), macaque CELA2B (90% identical), pig CELA2A (77% identical), rat Cela2a (72% identical), mouse Cela2a (70% identical), zebrafish ela2l (61% identical), zebrafish ela2 (59% identical), tropical clawed frog cela2a (59% identical). Paralogues in human: CELA2A (88% identical), CELA3A (55% identical), CELA3B (55% identical), CELA1 (52% identical), PRTN3 (33% identical), ELANE (31% identical).
Diseases named in the same sentence as CELA2B in open-access papers:
CELA2B is named in the same sentence as 5 diseases in open-access papers, as found by Europe PMC text mining. Sharing a sentence is not in itself a finding about the gene and the disease. The quoted sentences say what the papers report.
diabetes mellitus (1 paper, 2023). A metabolic disorder characterized by abnormally high blood sugar levels due to diminished production of insulin or insulin resistance/desensitization. "CELA3A is associated to exocrine pancreatic insufficiency and diabetes mellitus, whereas CELA2B is determinant of blood pressure and body mass index." (PMID 37021928, 2023).
diabetic retinopathy (1 paper, 2017). "Overall, the network effects of CASP9, CELA2A, CELA2B and DANJC16 on type 2 diabetes, especially diabetic retinopathy, worth further investigations." (PMID 28511641, 2017).
Pancreas Cancer (1 paper, 2023). "This confirms what already observed also in Section 3.2: a few genes such as CELA3A and CELA2B have an important role in Pancreas Cancer, and in particular their interplay with other genes change when the disease arises and develops." (PMID 37021928, 2023).
CELA2B also shares sentences with these, for which no sentence is quoted: exocrine pancreatic insufficiency (1 paper); type 2 diabetes (1).